PEBP4 (phosphatidylethanolamine binding protein 4)
Description:
Promotes AKT phosphorylation, suggesting a possible role in the PI3K-AKT signaling pathway.
Synonyms: PEBP-4; hPEBP4; CORK1; MGC22776; CORK-1; GWTM1933; HEL-S-300; PRO4408
Tractability: Antibody: UniProt places it where antibodies can reach, with high confidence; UniProt predicts a signal peptide or a membrane-spanning region; its Gene Ontology location is reachable by antibodies, with medium confidence.
Gene: Protein-coding gene on chromosome 8 (22,713,237 to 23,000,000, reverse strand). Ensembl gene ENSG00000134020.
Subcellular location: Secreted
Gene Ontology:
Molecular function: protein binding
Cellular component: extracellular exosome; extracellular region
Genetic constraint (gnomAD): Loss-of-function variants: 21 observed, 23.88 expected, observed/expected ratio (o/e) 0.88, 90% interval 0.62 to 1.27. The upper end of that interval is the gene's LOEUF score, 1.27, which puts it in group 5 of 6, group 1 being the genes least tolerant of losing a copy. Missense variants: 319 observed, 293.6 expected, observed/expected ratio (o/e) 1.09, 90% interval 0.99 to 1.19. Synonymous variants: 112 observed, 104.24 expected, observed/expected ratio (o/e) 1.07, 90% interval 0.92 to 1.26.
Homologues: Orthologues: chimpanzee PEBP4 (97% identical), macaque PEBP4 (88% identical), pig PEBP4 (75% identical), dog PEBP4 (74% identical), guinea pig PEBP4 (66% identical), rat Pebp4 (46% identical), mouse Pebp4 (46% identical), tropical clawed frog pebp4 (33% identical), zebrafish PEBP4 (25% identical), Drosophila melanogaster CG17919 (24% identical), Drosophila melanogaster CG10298 (23% identical), Drosophila melanogaster a5 (20% identical). Paralogues in human: PEBP1 (26% identical), MRPL38 (20% identical).
Diseases named in the same sentence as PEBP4 in open-access papers:
PEBP4 is named in the same sentence as 29 diseases in open-access papers, as found by Europe PMC text mining. Sharing a sentence is not in itself a finding about the gene and the disease. The quoted sentences say what the papers report.
lung carcinoma (6 papers, 2013 to 2024). "In lung cancer cells, overexpression of PEBP4 promotes the AKT and mTOR phosphorylation, while PEBP4 knock-down shows the opposite result." (PMID 38472560, 2024). "Previously published studies in humans have demonstrated that miR-15b suppresses PEBP4 expression and in turn contributes to metastasis and chemoresistance of lung carcinoma cells." (PMID 37280313, 2023). "In terms of individual molecules, most of them were studied in human cancers, including lung cancer (e.g., AQP1, AQP4, IL33, and PEBP4)." (PMID 35211471, 2022). "In lung diseases, available research on PEBP4 mainly focuses on lung cancer, yet the influence of PEBP4 on ALI has not been studied." (PMID 38472560, 2024). "PEBP4 and SFTPD have been reported as oncogenes in lung cancer." (PMID 33592039, 2021). "For example, PEBP4 could promote the proliferation, migration, and EMT of lung cancer." (PMID 35211471, 2022).
breast carcinoma (5 papers, 2013 to 2025). "PEBP4 expression was correlated with metastasis in colorectal and breast cancer but is significantly associated with better outcomes in our analysis." (PMID 37895248, 2023). "Knockdown of PEBP4 inhibited breast cancer cell proliferation in vitro and tumor growth in vivo." (PMID 37968615, 2023). "The genes most frequently affected by CNA deletions in breast cancer were EGR3 (3.8%), PEBP4 (3.7%), and TNFRSF10C (3.7%)." (PMID 40585280, 2025).
lung adenocarcinoma (3 papers, 2018 to 2021). A carcinoma that arises from the lung and is characterized by the presence of malignant glandular epithelial cells. "The overexpression of hsa-miR-15 can promote cisplatin resistance of lung adenocarcinoma cells by inhibiting the expression of phosphatidylethanolamine binding protein 4 (PEBP4)." (PMID 34818353, 2021). "Overexpression of miR-15b can promote thecisplatin chemoresistance of lung adenocarcinoma cellsby inhibiting the expression of phosphatidylethanolaminebindingprotein 4 (PEBP4)." (PMID 31376328, 2020). "miR-15b had a dual role in oral tongue squamous cell carcinoma (TSCC) and lung adenocarcinoma; through the regulation of TRIM14 it was implicated in the reversion of cisplatin resistance in TSCC, while it decreased sensitivity to cisplatin by targeting PEBP4 in lung adenocarcinoma." (PMID 30211115, 2018).
Hepatic fibrosis (2 papers, 2022 to 2024). The presence of excessive fibrous connective tissue in the liver. "To investigate the association between PEBP4 expression and liver fibrosis, we firstly measured the protein levels of PEBP4 in control and CCl4-treated WT mice by western blotting." (PMID 36120358, 2022). "Taken together, our findings indicate that PEBP4 deficiency aggravates liver fibrosis and activates the NF-κB signaling pathway, providing a novel insight into the roles of PEBP4 in diseases." (PMID 36120358, 2022). "Exacerbation of liver fibrosis based on PEBP4 knockout was further recognized by increased activities of ALT, AST and HYP, whose higher activities represent liver injury and fibrosis." (PMID 36120358, 2022). "In this study, we demonstrated the antifibrotic roles of PEBP4 by combining hepatocyte-specific PEBP4 knockout with carbon tetrachloride (CCl4)-induced liver fibrosis mice." (PMID 36120358, 2022). "On the basis of the decrease in PEBP4 expression in fibrotic liver, we then detected its role in hepatic fibrosis in PEBP4 CKO mice subjected to CCl4." (PMID 36120358, 2022). "In the current study, we firstly used a CCl4-induced fibrotic model, and identified that PEBP4 was downregulated in the liver of mice treated with CCl4, implying a potential involvement of PEBP4 in hepatic fibrosis." (PMID 36120358, 2022). "At any rate, the present findings highlight the protective role of PEBP4 in hepatic fibrosis and its potential molecular mechanism, providing a foundation for the clarification of its exact role in liver fibrosis." (PMID 36120358, 2022). "Although PEBP4 was reported to promote cancer development, our findings suggested that PEBP4 unexpectedly had beneficial effects in liver fibrosis." (PMID 36120358, 2022). "In conclusion, our research proved that PEBP4 can alleviate liver fibrosis and partly suppress the NF-κB pathway." (PMID 36120358, 2022). "To define the effect of PEBP4 on the NF-κB pathway in hepatic fibrosis, we performed the protein expression of the NF-κB pathway by western blotting assays." (PMID 36120358, 2022). "In addition, PEBP4 is closely related to acute liver injury and liver fibrosis on account of its anti-inflammatory and liver-protective effects." (PMID 38472560, 2024). "Previous studies found that knocking out PEBP4 could aggravate acute liver injury induced by LPS/D-GalN and liver fibrosis induced by CCl4 through the NF-κB signaling pathway, indicating PEBP4 may be a candidate regulator for inflammatory disorders." (PMID 38472560, 2024). "In this study, we generated a hepatocyte-conditional knockout (CKO) mouse model of PEBP4, and explored the potential functions of PEBP4 on liver fibrosis and the NF-κB signaling pathway in a mouse model of carbon tetrachloride (CCl4)-induced liver fibrosis." (PMID 36120358, 2022). "Taken together, these results indicate that the effect of PEBP4 knockout on liver fibrosis might be partly mediated by the NF-κB signaling pathway." (PMID 36120358, 2022). "Reasons for this inconformity might be that the functions of PEBP4 may be performed via different signaling pathways in liver fibrosis and cancer, in addition, the effect of PEBP4 is related to its expression level." (PMID 36120358, 2022). "Additionally, it would be better if we detect more downstream targets of the NF-κB and employ the model of PEBP4 overexpression to clarify the function of PEBP4 on liver fibrosis in our future studies." (PMID 36120358, 2022). "The discrepancy in the results indicates that the protective role of PEBP4 in liver fibrosis might be mediated by the NF-κB signaling, but also through other molecular pathways." (PMID 36120358, 2022). "Whether PEBP4 affects liver fibrosis via the suppression of HSC activation is worth investigating." (PMID 36120358, 2022).
Hepatic fibrosis (continued). "Phosphatidylethanolamine-binding protein 4 (PEBP4) is a secreted protein involved in regulating many molecular pathways, whereas its roles in diseases including hepatic fibrosis remain undefined." (PMID 36120358, 2022). "To further investigate the mediation of the NF-κB pathway in the deterioration effect of PEBP4 deletion on liver fibrosis, we firstly examined the effect of PDTC, an NF-κB pathway inhibitor, on liver fibrosis induced by CCl4." (PMID 36120358, 2022). "These research indicate that PEBP4 is potentially involved in many molecular pathways to modulate tumor pathogenesis, but its potential role in other diseases like hepatic fibrosis has not yet been discussed." (PMID 36120358, 2022).
lung squamous cell carcinoma (2 papers, 2013 to 2022). "For instance, overexpression of PEBP4 results in the PI3K/Akt and SHH pathways activation, whereas PEBP4 silencing activates the ERK and MAPKs pathways in lung squamous cell carcinoma." (PMID 36120358, 2022).
gastric cancer (1 paper, 2020). A primary or metastatic malignant neoplasm involving the stomach. "In gastric cancer, the PI3K-AKT pathway was shown to be induced by netrin-1 and phosphatidylethanolamine-binding protein 4 (PEBP4) both of which are proteins commonly found in many cancers." (PMID 32212786, 2020).
hepatocellular carcinoma (1 paper, 2022). A malignant tumor that arises from hepatocytes. "The present study explored the mechanism by which PEBP4 regulates the growth and progression of hepatocellular carcinoma cells." (PMID 35955931, 2022). "Altogether, our study suggests that increased expression of PEBP4 exacerbates malignant behaviors of hepatocellular cancer cells through cooperative participation of mTORC1 and mTORC2." (PMID 35955931, 2022). "Moreover, using hepatocellular carcinoma cell lines, we found that overexpression of PEBP4 enhanced malignant behaviors, including cell proliferation, migration, invasion, and metastasis, while its knockdown induced opposite changes." (PMID 35955931, 2022). "In the present study, we selected two hepatocellular carcinoma cell lines, MHCC97H with relatively high levels of PEBP4 and MHCC97L at its low levels, and then manipulated the expression levels of PEBP4." (PMID 35955931, 2022). "In the present study, we chose hepatocellular cancer cells whose PEBP4 expression was not previously examined." (PMID 35955931, 2022).
Infertility (1 paper, 2021). "The existing evidence suggests that, down-regulation of PEBP4 in cattleyak could compromise sperm maturation processes and result in infertility." (PMID 34311720, 2021).
liver diseases (1 paper, 2022). "However, there has been no report regarding the role of PEBP4 in liver diseases." (PMID 36120358, 2022).
renal fibrosis (1 paper, 2022). A final common manifestation of a wide variety of chronic kidney diseases characterized by glomerulosclerosis and tubulointerstitial fibrosis. "The status of NF-κB signaling modulated by PEBP4 could be similar to that regulated by microRNA-378, which activated NF-κB by targeting Prkag2, promoting renal fibrosis." (PMID 36120358, 2022).
steatosis (1 paper, 2022). Increased lipid within the cytoplasm of cells. "Histologically, HE staining revealed that PEBP4 deficiency aggravated CCl4-induced disorganized liver structure with steatosis as compared with the control groups." (PMID 36120358, 2022).
tumor (12 papers, 2013 to 2025). "The overexpression of PEBP4 is implicated in tumour growth, progression and metastasis, suggesting a useful diagnostic marker for neoplasms." (PMID 40364294, 2025). "PEBP4 impacts tumor survival rates by regulating AKT, MAPK, SHH, and other signaling pathways in human." (PMID 39194863, 2024). "We then employed Xenograft tumor model by injection of MHCC79H/sh-PEBP4 and MHCC79H/sh-NC cells, respectively." (PMID 35955931, 2022). "The results revealed that the growth of tumor significantly slowed down and at the endpoint, tumors from PEBP4 knockdown looked much smaller, and weight was greatly reduced." (PMID 35955931, 2022). "We first assessed the effect of PEBP4 shRNA on cell proliferation, colony formation, and tumor growth." (PMID 35955931, 2022). "In this study, we found that PEBP4 expression was decreased in ALI and PEBP4 CKO aggravated ALI, contrasting with the increased expressions of PEBP4 in tumor tissues and PEBP4’s promotion of tumor development." (PMID 35874667, 2022). "We then examined the effect of PEBP4 overexpression on cell proliferation, colony formation, and tumor growth." (PMID 35955931, 2022). "The overexpression of phosphatidylethanolamine-binding protein 4 (PEBP4) in LC regulates tumor progression, invasion, and metastatic potential, which may be partly due to an increase in PEs that act as agonists of PEBP and mediate signal transduction." (PMID 36902523, 2023). "Finally, knockdown of PEBP4 diminished the growth of tumor and metastasis, whereas they were enhanced by overexpression of PEBP4." (PMID 35955931, 2022). "Concomitantly, knockdown of PEBP4 suppressed the growth of tumor and metastasis derived from MHCC97H cells, whereas overexpression of PEBP4 enhanced the development of tumor and metastasis from MHCC97L cells." (PMID 35955931, 2022). "Similarly, PEBP4 knockdown can activate extracellular signal-regulated kinase 1/2 (ERK1/2) pathway, thereby inhibiting proliferation and migration in glioma cells, whereas its overexpression can potentiate tumor growth by stimulating PI3K/Akt/mTOR pathway in non-small cell lung cancer (NSCLC)." (PMID 36120358, 2022).
cancer (10 papers, 2013 to 2024). A tumor composed of atypical neoplastic, often pleomorphic cells that invade other tissues. "On the other hand, PEBP4 was found to positively regulate the phosphorylation of AKT in various cancer models." (PMID 38472560, 2024). "Several studies have identified PEBP4 in body fluids such as serum and cerebrospinal fluid in cancer and brain injury, suggesting its role outside cells." (PMID 35955931, 2022). "Altogether, our data indicate that PEBP4 participates in regulation of Akt/mTOR, leading to increased proliferation, migration, invasion, and metastasis of cancer cells." (PMID 35955931, 2022). "When PEBP4 is knocked down in cancer cells, the cell proliferation, migration, and invasion are reduced, and apoptosis is increased." (PMID 35955931, 2022). "Previous studies have reported that PEBP4 is overexpressed in a variety of cancer specimens and the expression is correlated to cancer progression." (PMID 35955931, 2022). "Previous studies have shown that the expression of PEBP4 is increased in many cancer specimens, which correlates to cancer progression." (PMID 35955931, 2022). "Collectively, our results suggest that PEBP4 overexpression in cancer cells promote their growth and progression through action on mTORC1 and mTORC2." (PMID 35955931, 2022). "At present, studies on PEBP4 have mostly focused on cancers." (PMID 35874667, 2022). "However, the argument on its inhibitory role in the activation of the ERK pathway sounds contradictory to the observations that the expression of PEBP4 is increased observed in many cancers." (PMID 35955931, 2022). "Therefore, our data from mechanistic points reinforces important roles of PEBP4 in cancer progression." (PMID 35955931, 2022). "Previous studies on PEBP4 revealed its anti-apoptotic and pro-metastatic roles in cancers." (PMID 36120358, 2022). "At cellular levels, it has been shown that knockdown of PEBP4 in cancer cells suppresses cell proliferation, migration, and invasion, leading to their apoptosis, whereas overexpression of PEBP4 induces opposite changes and confers resistance to chemotherapy and radiotherapy." (PMID 35955931, 2022). "Existing studies have revealed the effects of PEBP4 on multiple human cancers." (PMID 36120358, 2022). "Previous studies have indicated that PEBP4 promotes the progression of cancer." (PMID 35955931, 2022). "It is tempting to speculate that low levels of PEBP4 mainly function inside the cells and part is secreted if it is overexpressed, for example, in advanced stages of cancer." (PMID 35955931, 2022). "The expression of PEBP4 was low in immortalized normal hepatic cells (LO2) and hepatic-derived cancer cells of low malignancy (MHCC97L), while it was relatively high in more aggressive HCC (HCCLM3, MHCC97H) (p < 0.05 or p < 0.01)." (PMID 35955931, 2022). "Available studies on PEBP4 have mainly focused on cancers, and PEBP4 is highly expressed in cancer tissues, but the effects of PEBP4 expression on tissue damage have not been reported, which attracted our attention." (PMID 35874667, 2022).
infection (1 paper, 2022). The state of being infected such as from the introduction of a foreign agent such as serum, vaccine, antigenic substance or organism. "Compared with adenovirus-directed expression of GFP, the PEBP4 knockdown-induced reduction of cell proliferation, migration, and invasion was significantly rescued by infection of adenovirus encoding Akt S473D, although not completely." (PMID 35955931, 2022).
PEBP4 also shares sentences with these, for which no sentence is quoted: colorectal cancer (2 papers); ovarian carcinoma (2); rectal cancer (2); Alzheimer disease (1); B-cell lymphoma (1); Burkitt lymphoma (1); diffuse large B-cell lymphoma (1); entropion (1); hematologic malignancies (1); lung diseases (1); lymphoma (1); mantle cell lymphoma (1); non-Hodgkin lymphoma (1); ovarian tumour (1); prostate carcinoma (1).